UBE2Q2P2 (UBE2Q2 pseudogene 2)
Synonyms: formerly UBE2QP2; UBE2Q2P3
Gene: Transcribed unprocessed pseudogene on chromosome 15 (82,391,844 to 82,420,075, forward strand). Ensembl gene ENSG00000259429.
Diseases named in the same sentence as UBE2Q2P2 in open-access papers:
UBE2Q2P2 is named in the same sentence as 1 disease in open-access papers, as found by Europe PMC text mining. Sharing a sentence is not in itself a finding about the gene and the disease.
UBE2Q2P2 shares sentences with these, for which no sentence is quoted: cancer (1 paper).